RN7SL640P (RNA, 7SL, cytoplasmic 640, pseudogene)
Gene: Miscellaneous RNA gene on chromosome 9 (39,191,100 to 39,191,360, forward strand). Ensembl gene ENSG00000278825.
Homologues: Orthologues: chimpanzee Metazoa_SRP (99% identical). Paralogues in human: RN7SL343P (100% identical), RN7SL462P (100% identical), RN7SL422P (99% identical), RN7SL2 (82% identical), RN7SL3 (82% identical), RN7SL1 (81% identical), RN7SL464P (80% identical), RN7SL607P (79% identical), RN7SL597P (79% identical), RN7SL804P (79% identical), RN7SL655P (79% identical), RN7SL543P (78% identical), and 705 more.